STAT3 (signal transducer and activator of transcription 3)
Diseases named in the same sentence as STAT3 in open-access papers (continued):
Sharing a sentence is not in itself a finding about the gene and the disease.
T-cell lymphoma (continued). "Yet, another study showed a reverse effect, where STAT3 can suppress miR-26a expression in T-cell lymphoma (see Supplementary Discussion)." (PMID 27683108, 2016). "In T-cell lymphoma, STAT3 silencing reduces PD-L1 expression." (PMID 40297576, 2025). "Overall, these data indicate that IRF4 sustains the oncogenic properties of STAT3 in T-cell lymphomas, and that its inhibition represents an alternative avenue to interfere with STAT3 signaling and offers promising therapeutic opportunities to treat and prevent drug resistance in ALCL patients." (PMID 29346274, 2018). "It is unclear whether the pro-survival or protective potential of Hh signaling is mediated by activating STAT3 pathway in T cell lymphomas." (PMID 27275540, 2017). "Aberrant activation of Hh/GLI1 and STAT3 pathways usually occur in tumors, however their crosstalk is quite unknown in T cell lymphomas." (PMID 27275540, 2017). "This study mainly focuses on the Hh/GLI1 and STAT3/SOCS3 pathways in T-cell lymphomas." (PMID 27275540, 2017). "on T-cell lymphoma and hypothesized that it could be related to STAT3." (PMID 37324014, 2023). "We decided to determine the effect of NT1721 on STAT3 activation since several reports show that GLI1 inhibition or knockdown decreased phosho-STAT3 (pSTAT3) levels in T cell lymphomas and that pSTAT3 may be an important driver of CTCL, especially in advanced disease." (PMID 34282785, 2021). "Using cytokine array analyses, we found that IL-6 was increased in PI3K inhibitor-resistant B- and T-cell lymphoma cells, and showed that the acquired resistance to copanlisib and duvelisib reflected two mechanisms in common: upregulation of IL-6 and activation of STAT3/5." (PMID 31601188, 2019). "Additionally, NK/T-cell lymphomas can be driven by activation of STAT3 and may be rationale diseases to target with STAT inhibition." (PMID 30446007, 2018). "In T-cell lymphoma cells, TGM2 up-regulates the IL-6/JAK/STAT3 pathway, which proliferates the growth of T-cell lymphoma cells." (PMID 39115570, 2024). "The activation of STAT3 and STAT5B in feline alimentary T cell lymphomas is comparable to the human disease, therefore, we continued to analyse the genomic status of the respective STAT genes." (PMID 34680385, 2021). "The entire STAT3 gene and the hotspot SH2-domain of STAT5B were screened by targeted amplicon sequencing in 63 patients with T-cell lymphoma." (PMID 32188095, 2020). "For instance, in anaplastic lymphoma kinase (ALK)-carrying T-cell lymphoma, PD-L1 expression can be induced by ALK signal transducer, and this function is also observed in signal transducer and activator of transcription 3 (STAT3) in chemoresistant NSCLC." (PMID 31636634, 2019). "We found that protein expressions of GL11, p-STAT3, STAT3, and SOCS3 were up-regulated in T-cell lymphoma tissues and cell lines." (PMID 27275540, 2017). "It was worth mentioning that Fisher's exact probability test of the immunochemical results showed both p-STAT3 and SOCS3 protein expression were positively correlated with GLI1 in T-cell lymphomas with each P value<0.05." (PMID 27275540, 2017). "Analysis results showed that both p-STAT3 and SOCS3 protein expression were positively correlated with GLI1 in T-cell lymphomas with the P value as 0.06 and 0.021 respectively." (PMID 27275540, 2017). "Our study results showed that protein expressions of GL11, p-STAT3, STAT3, and SOCS3 were up-regulated both in T-cell lymphoma tissues and T-cell lines." (PMID 27275540, 2017). "We examined the expression of GLI1, p-STAT3, STAT3 and SOCS3 for tissues from 35 cases of T-cell lymphomas by immunohistochemistry, in comparation with the control of 15 cases of reactive hyperplasia of lymph node (RHL)." (PMID 27275540, 2017). "The CTLA4apt-STAT3 siRNA AsiC induced silencing of Stat3 in both CD8+ and CD4+ T cells led to reduced tumor growth in four different murine tumor models and human T cell lymphoma." (PMID 27827876, 2016).
T-cell lymphoma (continued). "Some evidence suggests that, in certain individuals with HIV-1 infection, proviral activation of STAT3—and in some cases, both STAT3 and LCK—may compensate for one or more steps required for the development of T-cell lymphomas." (PMID 40244051, 2025). "A body of evidence suggests that HIV-1 proviruses integrated into several oncogenes, such as signal transducer and activator of transcription 3 (STAT3) and lymphocyte-specific protein tyrosine kinase (LCK), thus paving the way for developing T-cell lymphomas 5,65,66." (PMID 37645926, 2023). "Chimeric nucleophosmin (NPM)/anaplastic lymphoma kinase (ALK) is significantly associated with malignant cell transformation and NPM/ALK-carrying T cell lymphoma (ALK + TCL) cells abundantly express PD-L1, which is regulated by STAT3, and knocking down STAT3 can inhibit this effect." (PMID 35907881, 2022). "STAT3 is commonly activated in tumor-infiltrating macrophages, and STAT3 can bind to the promoter of the CD274 gene required for PD-L1 gene expression in T-cell lymphoma." (PMID 33509150, 2021). "T-cell lymphoma cells carrying the oncogenic nucleophosmin/anaplastic lymphoma kinase (NPM/ALK), which is involved in malignant transformation, induce high levels of PD-L1 expression via STAT3 and ERK activation." (PMID 31341011, 2019). "STAT3 plays an important role in driving the Th17 differentiation of naïve CD4+ T cells, and it may also drive increased expression of IL-17 in T cell lymphoma." (PMID 31684088, 2019). "In our study, STAT3 and SOCS3 expression was simultaneously increased in T-cell lymphoma." (PMID 27275540, 2017). "We speculated that activation of GLI1 could activate p-STAT3 and SOCS3 expression directly or indirectly, and thereby activated Hh signaling resulting in T-cell lymphoma cell ontogeny." (PMID 27275540, 2017). "In addition, IL31 is highly expressed in hematological malignancies such as follicular lymphoma, germinal cancer derived B-cell malignancy, and T cell lymphoma, and was found to contribute to tumor growth via the STAT1/STAT3 signaling pathway." (PMID 28147314, 2017). "Although SOCS3 was described as a negative regulator of STAT3 in many malignancies, the exact role of SOCS3 in T-cell lymphoma was largely unknown." (PMID 27275540, 2017). "Moreover, the protein expressions of p-STAT3 and SOCS3 were positively correlated with GLI1 in T-cell lymphomas." (PMID 27275540, 2017). "The expressions of GLI1, p-STAT3, STAT3, and SOCS3 were detected respectively in 28/35(80.0%), 26/35(74.2%), 32/35(91.4%), and 24/35(68.6%) of T-cell lymphoma cases, when tumors displaying staining in 30% or more of the cells were categorized as positive cases." (PMID 27275540, 2017). "For example, in T cell lymphoma, VEGF upregulation was associated with activation of Jak-tyrosine kinase and JNKs activation but was independent of STAT3 activity." (PMID 21702955, 2011). "Because of the crosstalk between the JAK/STAT3 signaling pathway and many other oncogenic pathways (e.g., NF-κB, PI3K, and BCL2) in B- and T-cell lymphoma, combination therapy that targets JAK/STAT3 and additional oncogenic signaling pathways may increase the effectiveness of treatments." (PMID 31861597, 2019). "Although the STAT3 signaling pathway has been reported to regulate PD-L1 expression in the NPM/ALK-carrying T cell lymphoma (ALK + TCL) cells, BM cell interaction did not activate STAT3 in B16F10 tumor cells." (PMID 25889536, 2015).
lymph node metastasis (54 papers, 2009 to 2025). "Univariate analysis showed that lymph node metastasis, lymphatic vessel invasion, blood vessel invasion and p-STAT3 expression were associated with RFS." (PMID 35314590, 2022). "They found that positive STAT3 expression in patients is associated with poorly differentiated, advanced stage, lymph node metastasis." (PMID 29560131, 2018). "Seven studies, enrolling 464 patients with lymphatic node metastasis and 443 patients without lymphatic node metastasis, were included in the present meta-analysis of the association between p-STAT3 overexpression and lymph node metastasis." (PMID 28797050, 2017). "It has been shown that p-Stat3 immunoexpression was significantly associated with lymph node metastasis or tumour size in other malignancies." (PMID 19638983, 2009). "Immunohistochemistry revealed that STAT3 expression was strongly associated with lymph node metastasis, TNM staging, and survival, suggesting that STAT3 could function as a predictive biomarker for poor prognosis in GC." (PMID 35401182, 2022). "Furthermore, the expression of STAT3 in tumor tissues was significantly associated with a tumor, lymph node metastasis, and TNM stage in breast patients." (PMID 29423040, 2018). "However, STAT3-positive expression was associated with cancer tissue, depth of invasion and lymph node metastasis in AFPGC." (PMID 23382965, 2013). "The high expression of STAT3 was significantly associated with the pTNM stage (P < 0.05), and the increased expression of p-STAT3 was significantly associated with depth of invasion (pT), lymph node metastasis (pN), and pTNM stage (P < 0.05, P < 0.05, P < 0.05)." (PMID 36225196, 2022). "Furthermore, STAT3 expression and depth of invasion and lymph node metastasis were associated." (PMID 23382965, 2013). "Overexpression of STAT3 was associated with several poor clinical outcomes of CCA patients, including tumor size, vascular invasion, lymph node metastasis, shorter OS, and DFS." (PMID 41425711, 2025). "The activated levels of p-Stat3 have correlated with cell differentiation, the depth of infiltration, lymph node metastasis, TNM staging, suggesting a broad involvement in the development and progression of GC." (PMID 36454780, 2022). "Poor TNM stages and lymph node metastases were associated with higher levels of IL-6, p-JAK2, JAK2, p-STAT3, and STAT3 in patients with NPC." (PMID 36313702, 2022). "Shang found that the p-STAT3 expression level was associated with FIGO stage and lymph node metastasis and that STAT3 expression correlated with tumour grade and lymph node metastasis." (PMID 34789292, 2021). "A significant correlation was found between STAT3 protein expression and tumor differentiation, clinical stage, and lymph node metastasis of NSCLC patients." (PMID 31847229, 2019). "The activation of the STAT3 pathway and the increase in pY-STAT3 (Tyr705) expression directly correlated with higher clinical stage, lower degree of differentiation, presence of lymph node metastasis, and more reduced survival in EOC." (PMID 31861720, 2019). "In present study, we first found p-Stat3 was obviously expressed in cancerous tissue of GBC, and its expression was also significantly associated with clinical TNM stage, T stage and lymph node metastasis." (PMID 28061445, 2017). "Previous studies have reported that p-STAT3 inhibitor S3I-201 treatment inhibited lymph node metastasis and improved metastatic breast cancer outcomes." (PMID 27145366, 2016). "The expression levels of STAT3, p-STAT3 and HIF-1α, VM, status of lymph node metastasis and tumor differentiation degree were associated with the overall survival time of patients with GAC (P<0.05)." (PMID 24959290, 2014). "The immunohistochemistry results also showed that the phosphorylation of STAT3 was correlated with CCR7 expression in SCCHN, and CCR7 and STAT3 phosphorylation were all associated with lymph node metastasis." (PMID 25405202, 2014).
lymph node metastasis (continued). "For example, activation of Stat3 in thymic epithelial tumors, colorectal adenocarcinoma, and cutaneous squamous cell carcinoma correlates with invasion and lymph node metastasis." (PMID 20482858, 2010). "Positive expression of p-Stat3 was significantly associated with large tumour diameter (>4 cm), LVSI, and lymph node metastasis." (PMID 19638983, 2009). "Mutations in receptor tyrosine kinases, such as EGFR, and Src family proteins have been associated with the constitutive activation of STAT3 in NSCLC, and STAT3 activation has been associated with lymph node metastasis and clinical stage progression and is an independent prognostic factor of NSCLC." (PMID 36010693, 2022). "Seven studies (9 trials) investigated the association between STAT3/p-STAT3 expression and lymph node metastasis (yes vs. no) among a combined 750 cases." (PMID 34789292, 2021). "The level of p-STAT3 was correlated with pT, lymph node metastasis and pTNM stage." (PMID 32194797, 2020). "In addition, some studies found that STAT3 and p-STAT3 were overexpressed in laryngeal cancer tissues, and both were localized in the cytoplasm and nucleus, and related to clinical stage and lymph node metastasis." (PMID 30893785, 2019). "Based on GSVA, we identified 17 hallmark gene sets involved in lymph node metastasis, of which the upregulated hallmark gene sets IL6_JAK_STAT3_SIGNALING, REACTIVE_OXIGEN_SPECIES_PATHWAY,ANGIOGENESIS, HYPOXIA and APICAL_JUNCTION were reportedly associated with lymph node metastasis in cancer." (PMID 31832020, 2019). "We found that high STAT3 expression correlated with multi malignant clinicopathological characteristics, including gross tumor size, pathological satellite, vascular invasion, undifferentiated-type histology, lymph node metastasis and TNM stage." (PMID 28032598, 2017). "Sensitivity analysis for p-STAT3 expression with Lymph node metastasis." (PMID 27504822, 2016). "In addition, we pooled the OR between p-STAT3 expression and lymph node metastasis by fixed effects model, compared with the random effects model, and no obvious difference was found (OR: 2.11; 95% CI: 1.61–2.76; P <0.001; I2 = 79%)." (PMID 27504822, 2016). "Ten studies presented data about p-STAT3 expression and lymph node metastases, a combined OR of 2.108 revealed the positive relationship between increased p-STAT3 expression and positive N status (OR = 2.108, 95% CI: 1.104–4.024, P = 0.024, I2 = 82.1%, Ph<0.001)." (PMID 26024373, 2015). "Furthermore, STAT3 expression is reported to be correlated with lymph node metastasis, and higher expression of STAT3 and pSTAT3 indicates a worse prognosis." (PMID 20433750, 2010). "Other studies note that STAT3 was highly expressed in over 50% of NSCLCs, and an increased STAT3 expression level acted as a poor prognosis biomarker, predicting poor differentiation of cancer cells, lymph node metastasis, a low survival rate, and drug resistance." (PMID 39152779, 2024). "Moreover, despite the relatively low numbers of patients with complete data, STAT3 overexpression was significantly associated with the depth of invasion and lymph node metastasis (p<0.05) in the AFP-positive and -negative groups." (PMID 23382965, 2013). "The expression of p-STAT3 in non-small-cell lung cance (NSCLC) has also been illustrated to be interrelated with stage, differentiation, lymph node metastasis, and prognosis." (PMID 37450039, 2023). "This meta-analysis demonstrated that STAT3 is related to the diameter of thyroid cancer tumors, TNM staging, and lymph node metastasis." (PMID 35463085, 2022). "Our study demonstrated that higher STAT3 and p-STAT3 expression was correlated with FIGO stage, tumour grade, and lymph node metastasis." (PMID 34789292, 2021). "The expressions of IL-6, STAT3, p-STAT3, JAK2, p-JAK2 and CyclinD1 in NPC tissues were higher and correlated with TNM stage and lymph node metastasis (LNM)." (PMID 34165442, 2021).
lymph node metastasis (continued). "In this study, we investigated the relationship between STAT3/p-STAT3 expression and 3 major pathological characteristics (FIGO stage, tumour grade, and lymph node metastasis)." (PMID 34789292, 2021). "High expression levels of STAT3 in invasive breast cancer correlates with lymph node metastases, VEGFC/D, and VEGFR3 expression; therefore, STAT3 may play an indirect role in promoting lymphangiogenesis during involution." (PMID 38218743, 2024). "The STAT3/p-STAT3 overexpression also correlated with FIGO stages (I–II vs. III–IV) (OR = 0.36, p < 0.00001), tumour grades (G1 + G2 vs G3) (OR = 0.55; p = 0.001) and presence of lymph node metastasis (OR = 3.39; p < 0.00001)." (PMID 36768291, 2023). "The results showed significantly lower STAT3/p-STAT3 expression in lymphatic metastasis patients than in those without lymph node metastasis (OR = 3.39, 95% CI = 2.39–4.81, p < 0.00001)." (PMID 34789292, 2021). "The p-STAT3 expression in patients with the presence of lymph node metastasis was 2.43 times higher than the patients without the lymph node metastasis." (PMID 27504822, 2016). "Using Kaplan-Meier univariate analysis, six factors were found to have statistically significant associations with the OS time of patients with GAC following curative surgery, including STAT3, p-STAT3, HIF-1α, VM, status of lymph node metastasis and degree of differentiation (P<0.05)." (PMID 24959290, 2014). "PTEN and STAT3 were correlated with pathological grade (p=0.011, p=0.001, respectively), but not with tumor size, lymph node metastasis or clinical stage." (PMID 23170117, 2012). "Their report showed that p-Stat3 expression did not significantly correlate with any clinicopathological factors such as patient's age, tumour grade, disease stage, lymph node metastasis, or histological type." (PMID 19638983, 2009). "In addition, the expression of STAT3 and pSTAT3 in the group with lymph node metastasis is significantly higher than that in the group without lymph node metastasis." (PMID 34404767, 2021). "Furthermore, the p‐STAT3 level was significantly different in tumour size and lymph node metastasis, rather than other clinical characteristics, including age, sex, tumour node metastasis stage and recurrence risk stratification." (PMID 32285621, 2020). "Besides, we also found that STAT3 is negatively correlated with thyroid cancer tumor diameter and TNM stage (OR = 0.13, 95% CI (0.05, 0.33), p < 0.001; OR = 0.40, 95% CI (0.24, 0.67), p < 0.001), but positively correlated with lymph node metastasis (OR = 2.83, 95% CI (1.08, 7.46), p = 0.035)." (PMID 35463085, 2022). "However, information on clinicopathological factors seemed insufficient to draw any conclusions; approximately half the data on tumour grade, disease stage, and lymph node metastasis were not identified, and the researchers did not mention the prognosis of patients with p-Stat3 immunoexpression." (PMID 19638983, 2009). "The expression levels of STAT3 and PSTAT3 are higher in the group with lymph node metastasis than in the group without lymph node metastasis." (PMID 37853445, 2023). "STAT3 repression in Stages I and II, and the lack of STAT3 repression in Stages IIIC and IV, is concordant with the absence and presence of lymph node metastases, respectively, in these groups." (PMID 35328698, 2022). "STAT3/p-STAT3 overexpression was significantly correlated with FIGO stage (I-II vs. III-IV) (OR = 0.36, p < 0.00001), tumour grade (G1 + G2 vs. G3) (OR = 0.55; p = 0.001) and lymph node metastasis (yes vs. no) (OR = 3.39; p < 0.00001)." (PMID 34789292, 2021). "Notably, STAT3-, p-STAT3- and HIF-1α-positive expression and VM formation in tissues from patients with lymph node metastasis were significantly higher than those from patients without lymph node metastasis, respectively (92.7 vs. 57.9, 75.6 vs. 21.1, 78.0 vs. 31.6 and 41.5 vs. 10.5%; P<0.05)." (PMID 24959290, 2014).